TNF (tumor necrosis factor)
Diseases named in the same sentence as TNF in open-access papers (continued):
Sharing a sentence is not in itself a finding about the gene and the disease.
tumor (continued). "Tumor cells themselves and the surrounding normal cells have the ability to secrete TNF-α that is a strong promoter of interleukin (IL)-6, another cytokine, that influences ERK/MAPK signaling pathway and thus, may show anti-proliferative and pro-apoptotic effect in PC-3 cell." (PMID 24168453, 2013). "Therefore, many kinds of tumor cells are resistant or tolerant to TNF-induced apoptosis, although TNF may lead to apoptosis via the FADD-caspase pathway and the TRAF2-JNKK2 pathway." (PMID 23635099, 2013). "Indeed, most tumor cells and vessels of normal tissues are resistant to TNF." (PMID 24062984, 2013). "In addition, tumor cells producing TNFα are correlated with poor prognoses." (PMID 23997800, 2013). "Moreover, we demonstrate therapeutic mechanism of antitumor immune response mediated by oncolytic Ad co-expressing IL-23 and p35, showing that antitumor immunity is associated with the generation and recruitment of IFN-γ- and TNF-α-co-producing T cells in tumor microenvironment." (PMID 23844018, 2013). "Next, we analyzed immune cell infiltration into Panc02-FUGLW tumors grown in either C57Bl/6 wild type or C57Bl/6 mice deficient for TNF, TNFR1 or TNFR2 to address whether the loss of tumor control might be related to changes in the immune cell infiltrate of the tumor." (PMID 24098720, 2013). "An ability to induce irritation and inflammation is a common property of tumour promoters, and the importance of irritation in tumour promotion is consistent with the suggestion that pro-inflammatory cytokines, notably TNF-α, are of critical importance in this process." (PMID 23381142, 2013). "However, TNF induces multiple pathways including cell proliferation and survival processes that may facilitate tumor development." (PMID 23635099, 2013). "The production of chemokines and cytokines such as TNF-α, IL-6, and IL-1β by activated macrophages plays a critical role in diverse physiological processes, particularly in a host's innate immunity system to inhibit microbial growth, tumor cell growth, and tumor metastasis." (PMID 24574581, 2013). "Besides its key role in inflammation, TNF-α has several qualities that may have impact on carcinogenesis, tumor growth, and the time point of clinical detection of malignancies." (PMID 23762724, 2013). "Furthermore, it is of interest to elucidate whether the secretion of TNFα elicited from NK cells upon interaction with tumor targets is still effective in the presence of statins." (PMID 23667543, 2013). "Actually, we observed macrophage enhancing activity even after one week of etodolac feeding before tumor cell injection in that these mice had more activated peritoneal macrophages and adipose tissue macrophages and consequently produced more serum TNFα and IL-12 against LPS challenge." (PMID 23667623, 2013). "TNF-α may also act concomitantly with IFN-γ to block tumor stroma formation." (PMID 22235273, 2012). "In the 16th week, the cytokines IL-10, IL-17, TGF-β and TNF-α were detected at the highest overall level, creating a chronic inflammation cytokine milieu that may lead to antitumour immunity eradication and accelerated tumour progression." (PMID 23176085, 2012). "TNF is a pleiotropic cytokine, which when strategically delivered to tumours locally, may result in therapy-induced inflammation that could be protective against tumours." (PMID 23326670, 2012). "Interestingly, triptolide was shown to sensitize tumor cells to TNFα-induced apoptosis." (PMID 22545132, 2012). "On the other hand, chronic production of low doses TNF-α could sustain tumor growth." (PMID 23109839, 2012). "The inflammatory component of a neoplasm includes a diverse leukocyte population loaded with an assorted array of cytokines, cytotoxic mediators including reactive oxygen species, proteases, membrane-perforating agents and soluble mediators of cell killing such as TNF-α and IFNs." (PMID 22108515, 2012).
tumor (continued). "In addition, miR-222, by targeting PTEN and tissue inhibitor of metalloproteinases-3 (TIMP3) tumor suppressors, induces tumor necrosis factor (TNF)-related apoptosis-inducing ligand resistance and enhances cellular migration through activation of the Akt pathway and metallopeptidases." (PMID 23028614, 2012). "Tumor vascular targeting by TNF-α with chemotherapeutic drug GNGRG peptide or coupling this peptide to the surface of liposomal DXR could augment the penetration of chemotherapeutic drugs in subcutaneous tumor models and therefore serve as a novel treatment strategy for neuroblastoma." (PMID 21876694, 2012). "Indeed, inhibition of NFκB through adenoviral delivery of a modified form of IκB, a specific inhibitor of NFκB, has been reported to sensitize chemo-resistant tumours to the apoptotic potential of TNF-α and to the chemotherapeutic compound CPT-11, resulting in tumour regression." (PMID 23905066, 2012). "Similarly, the anti-tumor effect of Cl-IB-MECA alone was abrogated in mice injected with TNF-α mAb." (PMID 23028986, 2012). "TNF is a multifunctional cytokine first isolated from the serum of Bacillus Calmette-Guerin- (BCG-)infected mice treated with endotoxin that could induce hemorrhagic necrosis of tumours in mice." (PMID 23326670, 2012). "Indeed, among the various sub-populations of anti-tumour CD4+ T cells, CD4 Th1 cells are of particular interest through their ability to enhance the function of antigen presenting cells and to target the tumour stroma and angiogenesis through the secretion of TNF-α and IFN-γ." (PMID 23284752, 2012). "Therefore, it is conceivable that low amounts of TNF within a chronically inflamed tumour microenvironment may help drive tumour cells to undergo epithelial to mesenchymal plasticity and spread to form secondary tumours." (PMID 23326670, 2012). "TNF also has a role in neovascularisation, which may have implications for tumour angiogenesis." (PMID 23326670, 2012). "Therefore, understanding the molecular and biochemical mechanisms of tumour cell resistance to the cytotoxic action of TNF-α may ultimately provide new approaches to enhance the therapeutic effectiveness of TNF-α against human malignancies." (PMID 22719951, 2012). "The lower serum albumin concentration in advanced cancer patients may be due to the release of some cytokines such as interleukin 6 or TNF, to suppression of hepatocyte production of albumin, or to increased capillary permeability to albumin by the tumor or its surrounding tissues." (PMID 22559838, 2012). "In addition to their ability to promote the release of CCL2 and CCL5 by the tumor cells, it is possible that TNFα and IL-1β act directly to elevate processes that are required for local recurrence or metastasis formation, which identify the IDC-with-relapse group of patients." (PMID 21486440, 2011). "Unlike normal endothelium, tumour-associated endothelial cells often display an inflamed phenotype due to activation by cytokines emanating from the tumour including tumour necrosis factor-α (TNF-α) and interferon-γ (INF-γ)." (PMID 20965218, 2011). "Tumor necrosis factor-α(TNF-α)and other cytokines have been implicated in promoting a low-energy intake with increased energy expenditure and negative energy balance, likely due to tumor growth." (PMID 21350723, 2011). "The putative biological mechanisms may include direct effects of reactive oxygen/nitrogen intermediates and TNFα released by the M1 macrophages in close proximity to the tumor cells, and/or indirect effects through activation and recruitment of cytotoxic T cells." (PMID 20338029, 2010). "Although activated macrophages are the major source of TNF-α, it can also be produced by a variety of other cells, such as fibroblasts, astrocytes, Kupffer cells, smooth muscle cells, keratinocytes and a wide variety of tumour cells, including B-cell lymphoma, breast and colon carcinomas." (PMID 20087353, 2010).
tumor (continued). "Furthermore the intrabody strategy might be used to block TLR2 specific TNFα secretion of myeloid cells induced by factors secreted from tumour cells promoting metastasis." (PMID 20388199, 2010). "In addition, TAM-derived inflammatory cytokines (IL-1β, TNFα) may stimulate tumor cells to enhance the production of VEGF, and to produce angiogenin, a potent proangiogenic protein." (PMID 20822533, 2010). "We have thus unraveled a novel molecular mechanism of how loss of the tumor suppressor Smad4 may promote the carcinogenic process in vivo, where tumor cells interact with stromal cell types and respond to inflammatory cytokines like TNFα expressed by macrophages at the tumor host interface." (PMID 20307265, 2010). "Finally, TNF-α also confers an invasive and transformed phenotype onto tumour cells." (PMID 20087353, 2010). "Similarly, TNFα increased secretion might exert an anti-tumour effect on colon cells, even if its role in CRC is still controversial." (PMID 20717114, 2010). "In addition, TNF-α has also been shown to induce apoptotic and necrotic tumor cell death in vitro." (PMID 20178622, 2010). "TNF-alpha is a potent pleiotropic proinflammatory cytokine that is produced by various type of cells including macrophages, neutrophils, fibroblasts, keratinocytes, NK cells, T and B cells, and tumor cells and affecting growth, differentiation, cellular function and survival of all cells." (PMID 20920206, 2010). "For instance, in vivo, treatment of tumor-bearing animals with interleukin-12 (IL-12) shifts tumor-associated macrophages from a dominant M2 profile (elevated expression of TGFβ, IL-10, and MCP1) to a proimmunogenic/inflammatory M1 profile (elevated expression of IL-6 and TNFα)." (PMID 20508742, 2010). "However, TNFα production stimulated by ligation with antibody-coated tumor cells was significantly inhibited in IFNγ primed macrophages treated with Ly294002 indicating that the PtdIns 3-kinase/Akt pathway is involved in FcγR-mediated TNFα production." (PMID 19148288, 2009). "We checked whether Liqi interfered in the LPS-induced TNF-α activity in tumor bearing mice." (PMID 19570195, 2009). "The tri-cell complex of T-lymphocytes, tumor cells and accessory cells induces efficient tumor cell killing, which results from an activating "crosstalk" via cytokines (like e.g. IL-2, IL-12 and TNF-α) and costimulatory molecules between different immune cell types." (PMID 19216794, 2009). "Therefore, even though carcinoma cell proliferation is slightly inhibited the increased motility of these cells induced by TNF-α may augment the spread of the tumor." (PMID 18257926, 2008). "However, paradoxically to its name and anticipated biological behaviour TNF-α can also have different effects which may promote tumor growth and metastasis." (PMID 18257926, 2008). "Next, we assessed whether DCs electroporated with tumor cell RNA (RNA-DCs) or pulsed with UV-irradiated tumor cells (UV-DCs) and matured with TNF-α and LPS differ in vitro in their ability to induce proliferation of allogeneic lymphocytes or to migrate towards lymphoid organ chemokines." (PMID 18445282, 2008). "However it has been suggested that TNF on tumour vasculature has a direct anti-tumour mechanism." (PMID 18045456, 2007). "Additionally, TNFα induces iNOS and NO production and could mediate tumour promoter-induced transformation." (PMID 18045456, 2007). "Therefore, tumor-induced cytokines, such as TNF-α, may be responsible for the faster MHC isoform profile evident in plantaris muscles from TB rats." (PMID 17678552, 2007). "In order to examine the differences between IFN-DC and conventional IL-4/TNF-DC, we compared the morphology, immunophenotype, functional efficacy and gene expression profiles of these cell preparations with regard to their usefullness in anti-tumor vaccination strategies." (PMID 17894866, 2007).
tumor (continued). "However, when chronically produced TNF may act as an endogenous tumour promoter, contributing to tissue remodelling and stromal development necessary for tumour growth and spread." (PMID 16641913, 2006). "TNF-α is implicated in tumour-induced bone resorption and non-tumour-induced osteopenia." (PMID 16271143, 2005). "It was thought that the anti-tumor activity of TNF may co-activate some chemotherapy drugs." (PMID 15485573, 2004). "Several in vitro clonogenic assays suggest that an additive or a supra-additive interaction may occur between TNFα and ionising radiation as well as an enhancement of the antitumour effect of radiation in some murine and human tumours in vivo." (PMID 14612914, 2003). "However in the BN-175 tumour addition of TNF-α resulted in a strong synergistic effect." (PMID 12610519, 2003). "Thus, those patients who had the uncommon allele at TNF+488 and TNF−859 were more likely to present with a moderately differentiated (Grade 2) tumour than those patients without the uncommon allele." (PMID 12966432, 2003). "TNF may increase vascular permeability as well as induce endothelial cell apoptosis, possibly mediated by reduced αvβ3 integrin-mediated tumour endothelial cell adhesion." (PMID 12177785, 2002). "However, this can remain only speculative until studies in tumour biopsies estimating local IL-1 and TNF-α mRNA production by in situ hybridisation techniques before and after taxane chemotherapy are carried-out." (PMID 12085250, 2002). "Finally, DMXAA induces tumour haemorrhagic necrosis in TNF knockout hosts." (PMID 12177785, 2002). "Also, inhibition of the SCC Ag-1 expression in tumour cells by transfection of antisense SCC Ag-1 cDNA was accompanied by significantly increased sensitivity of these cells to apoptosis induced by etoposide or TNF-α." (PMID 10732775, 2000). "As TNF-alpha has been shown to up-regulate TP expression in tumour cells in vitro we performed an immunohistochemical study to investigate the possibility that TNF-alpha may be involved in the regulation of TP expression by malignant breast epithelial cells in vivo." (PMID 9649140, 1998). "Daily intragastric administration of Pt517 significantly inhibited tumor growth in mice; increased the expression levels of TNF-α, INF-γ, and CD8 in tumor tissues; and decreased the levels of IL-6, IL-10, and TGF-β." (PMID 42121906, 2026). "In the TCGA CCA cohort, high expression of IL6, TNF, AKT1, and STAT3 and low expression of PPARG correlated with advanced tumor stage and poorer overall survival (e.g., IL6: ρ = 0.42, p = 0.01)." (PMID 41899527, 2026). "Mechanistically, tumor-infiltrating CAR-T cells play a dual role: they release antitumor effector molecules (e.g., IFN-γ, TNF-α), but also produce CCL5, which promotes tumor growth by inducing VEGF and angiogenesis." (PMID 42089445, 2026). "GO analysis revealed enrichment of tumor necrosis factor (TNF) production, immune effectors, and cytokine/chemokine‐mediated signaling in both tumors and adjacent non‐tumor tissues (bottom)." (PMID 41133886, 2026). "In RCC, we observed an increased proportion of exhausted CD8+ T cell subsets, along with a decreased proportion of TNF+ MCs, suggesting the presence of a suppressive immune microenvironment within RCC tumor tissues." (PMID 40932351, 2026). "To investigate the ameliorative effects of ginsenoside Re on UVB-induced inflammation and oxidative stress in skin photodamage, we measured the levels of CAT, SOD, GSH-Px, MDA, T-AOC, IL-6, IL-8, and TNF-α in rat skin tissues." (PMID 41596360, 2026). "Mechanistically, abundant cytokines (TNF-α, FGF) in the IE tumor microenvironment promote FASN and PARP9 expression." (PMID 41969226, 2026).
tumor (continued). "Monocyte subsets 3 and 4 and MG1—the immune populations most enriched within tumor regions—received the strongest incoming signals via tumor-promoting networks such as galectin, complement, TGF-β, SPP1, TNF, and IL-4." (PMID 41503214, 2026). "We examined the genomic features of a GBM developing after prolonged TNF-α inhibitor therapy to explore potential links between TNF-α blockade, and tumor evolution." (PMID 42130630, 2026). "At the same time, miR-32-5p increases production of M1-type proinflammatory factors such as CD86, CCL2, tumor necrosis factor-α (TNF-α), and interleukin-6 (IL-6), thereby enabling macrophage polarization toward tumor-suppressive phenotype." (PMID 41608526, 2026). "Accumulating evidence indicates that inflammatory mediators-including CCL2, CCL3, CCL5, CXCL1, CCL20, TNF-α, IL-6, IL-8, and TGF-β-contribute to tumor growth, metastasis, immune modulation, and therapeutic resistance." (PMID 42245673, 2026). "In vivo, OF12-GEL significantly suppressed tumor growth in both DMBA-induced SCC rats and A431 xenograft mice, reducing tumor volume by and improving survival to 60%, and markedly downregulating BCL-2, Ki67, TNF-α, and ABCB1." (PMID 41705136, 2026). "MCs express high levels of c-kit (involved in development, survival, and migration) and its ligand SCF, which enhances tumor growth by stimulating cytokines such as VEGF, TNF, IL-6, and IL-1." (PMID 41596472, 2026). "Its anti-tumor activity was evaluated in a CT-26 tumor-bearing mouse model through histopathology, tumor inhibition rate, immune organ indices, and serum cytokine (IFN-γ, TNF-α, IL-2) assays." (PMID 41815917, 2026). "HA@Ag NPs/PTX Cls eliminated intratumoral bacteria, restoring microbial homeostasis, enhancing MHC-I antigen presentation, increasing production of tumor necrosis factor (TNF) and interferon (IFN), and downregulating PD-L1 to promote tumor immunorecognition." (PMID 42164099, 2026). "CD8+ T cell-specific Topk deletion increased granzyme B (GzmB), tumor necrosis factor-α (TNF-α), and interferon-γ (IFN-γ) secretion and improved tumor control." (PMID 41868885, 2026). "These invading cells also release pro-inflammatory substances like interleukin-6 (IL-6) and tumor necrosis factor-alpha (TNF-α), which in turn promote tumor growth, metastasis, and therapy resistance." (PMID 41614944, 2026). "TNF+ MCs recruit immune cells through pro-inflammatory actions, while VEGFA+ MCs support tumor growth and suppress immune responses." (PMID 40932351, 2026). "Pro-inflammatory cytokines such as TNF-α, IFN-β, and IL-6 were significantly elevated in tumor tissues and serum compared to those in the PBS group." (PMID 41583068, 2026). "In contrast, MG3, MG4, and monocyte subsets 1 and 2—which were less concentrated within tumor cores—exhibited significantly weaker engagement with pro-tumor or immunosuppressive pathways, including MIF, TNF, IL-4, IL-6, OSM, galectin, and TGF-β." (PMID 41503214, 2026). "After two vaccinations, splenocytes from ICC@G-PL-vaccinated mice co-cultured with tumour cells produced more IFN-γ and TNF-α spots (ELISPOT) and secreted higher levels of these cytokines (ELISA), indicating tumour-specific T cell development." (PMID 41510149, 2026). "This polarization pattern extended to TNF‐α compartments, with elevated AREG+TNF‐α− populations and diminished AREG−TNF‐α+ subsets in tumor microenvironments." (PMID 41082397, 2026). "In vivo, intratumoral injection of P. aeruginosa led to increased expression of TNF-α, IFN-γ, and PD-L1 within tumor tissues, as well as significant maturation of DCs and CD8+ T cells." (PMID 41484455, 2026). "Examination of tumor-infiltrating immune cells in recipients treated with anti-PD-1 showed that 6PGD deficiency in MDSCs or 6AN administration enhanced the frequency of tumor-infiltrating CD8+ cells and TNF+ CD8+ T cells." (PMID 41535266, 2026).